CUL4B (cullin 4B)
Diseases named in the same sentence as CUL4B in open-access papers (continued):
Sharing a sentence is not in itself a finding about the gene and the disease.
glioma (3 papers, 2017 to 2021). A benign or malignant brain and spinal cord tumor that arises from glial cells (astrocytes, oligodendrocytes, ependymal cells). "To investigate if CUL4B is associated with the progression of glioma, we first examined CUL4B protein levels in 29 tumor samples and paired adjacent non-malignant tissues by Western blot." (PMID 33869025, 2021). "We found that CUL4B level was upregulated in glioma tissues and a higher CUL4B level was associated with poor overall survival in glioma patients." (PMID 33869025, 2021). "To verify this hypothesis, we used glioma patient samples to analyze the association between CUL4B expression and TMZ resistance, and GBM cell lines to further investigate the role of CUL4B in TMZ resistance and the underlying mechanism." (PMID 33869025, 2021). "The association between CUL4B and glioma were further analyzed using CGGA database." (PMID 33869025, 2021). "The results showed a significant positive correlation between SIRT1 and CUL4B expression and lymphoid neoplasm diffuse large B-cell lymphoma, brain lower grade glioma, pancreatic adenocarcinoma, and thymoma." (PMID 34163012, 2021). "CUL4B elevation positively correlated with advanced pathological stage, tumor recurrence, malignant molecular subtype and poor survival in glioma patients receiving TMZ treatment." (PMID 33869025, 2021). "Both the recurrent gliomas and GBMs showed significantly higher CUL4B expression than primary tumors." (PMID 33869025, 2021). "Survival analysis revealed that glioma patients with higher CUL4B expression levels exhibited shorter survival durations." (PMID 33869025, 2021). "Analysis of CUL4B expression using CCGA database revealed that high CUL4B expression correlated with poor survival in glioma patients receiving TMZ therapy." (PMID 33869025, 2021). "It has been reported that CUL4B promotes proliferation of glioma cells." (PMID 33869025, 2021). "Western blot and public datasets analysis showed that CUL4B was upregulated in glioma specimens." (PMID 33869025, 2021). "To extend these observations, we examined CUL4B expression in primary and recurrent gliomas." (PMID 33869025, 2021). "Moreover, high expression of CUL4B also correlated with poor prognosis in both primary and recurrent glioma patients." (PMID 33869025, 2021). "CUL4B level in low-grade gliomas (LGGs, grade II) was slightly higher than that of adjacent non-malignant tissues, whereas CUL4B expression was notably elevated in more aggressive high-grade gliomas (HGGs, grade III and IV GBM), comparing to the paired non-cancerous tissues." (PMID 33869025, 2021). "In summary, the results of this study indicate that CUL4B promotes TMZ resistance in GBM cells by epigenetically repressing CDKN1A transcription, CUL4B is a significant clinical prognostic factor and may serve as a promising therapeutic target for the treatment of gliomas." (PMID 33869025, 2021). "Therefore, we hypothesize that CUL4B may promote TMZ resistance through enhancing TMZ-induced senescence in glioma cells." (PMID 33869025, 2021). "However, whether CUL4B is involved in TMZ resistance in glioma is unknown." (PMID 33869025, 2021). "Given the importance of CUL4B expression in patient survival and the critical roles of TMZ resistance in glioma prognosis, we speculated that CUL4B might be involved in TMZ resistance." (PMID 33869025, 2021).
lymph node metastasis (3 papers, 2020 to 2025). "Still, it was not an independent prognostic indicator in PTC, probably because the impact of CUL4B on recurrence was related to many other factors, such as histological subtypes and lymph node metastasis." (PMID 40203790, 2025). "Notably, primary tumors with lymph node metastasis (LNM) exhibited higher level of CUL4B expression than those without LNM." (PMID 32054830, 2020).
Obesity (3 papers, 2016 to 2025). Accumulation of substantial excess body fat. "The main clinical manifestations of CUL4B gene variant patients are neurological abnormalities, short stature, obesity, and reproductive tract abnormalities." (PMID 39773765, 2025). "The RNA-seq data show that the type 2 diabetes, PPAR pathway and insulin signaling are enriched in KOIEC tissue, which is in accordance with our previous reports that adipocyte specific Cul4b knockout mice are susceptible to obesity." (PMID 35197566, 2022). "This set of genes includes the X-linked Cul4b, which has previously been associated with syndromic obesity in humans, and Man2c1 which has been associated with a gonadal fat pad QTL on chromosome 9 in mice." (PMID 27506198, 2016).
rheumatoid arthritis (3 papers, 2021 to 2025). A chronic, systemic autoimmune disorder characterized by inflammation in the synovial membranes and articular surfaces. "In rheumatoid arthritis (RA), circ_0011058 alleviates pathology through the circ_0011058/miR-335-5p/CUL4B signal axis, suggesting a potential therapeutic target for RA." (PMID 40230836, 2025).
cerebral malformation (2 papers, 2017 to 2019). Disorders of the developing brain that constitute a wide variety of complex malformations that account for a significant fraction of childhood onset epilepsy, intellectual disability, and autism. "They provided first evidence that there was a firm association between CUL4B variants and cerebral malformations." (PMID 28630798, 2017). "The interaction between CUL4B and WDR62 might contribute to the development of cerebral malformations in patients with CUL4B variants." (PMID 28630798, 2017).
diffuse large B-cell lymphoma (2 papers, 2021 to 2025). "Although CUL4B regulates autophagy via the JNK signal in diffuse large B-cell lymphoma, its role in autophagy has not been reported in other cancers and studies." (PMID 34163012, 2021).
liver cancer (2 papers, 2017 to 2020). An epithelial or non-epithelial malignant neoplasm that arises from the liver. "In bladder cancer, liver cancer and non-small cell lung cancer, Cul4B plays the role of oncogene by inhibiting the expression of tumor suppressor gene." (PMID 32622365, 2020). "Cul4B can inhibit the expression of Wnt/β pathway antagonists and activate Wnt/β-catenin signaling pathway to promote the development of liver cancer." (PMID 32622365, 2020).
lymphoma (2 papers, 2022 to 2025). A malignant (clonal) proliferation of B- lymphocytes or T- lymphocytes which involves the lymph nodes, bone marrow and/or extranodal sites. "In B cells, CUL4B upregulation stimulates immune responses but is linked to an unfavorable prognosis in lymphoma." (PMID 40230836, 2025). "In other studies, loss of CUL4B has been described as conferring resistance to lenalidomide in lymphoma and myeloma cell lines 100,101." (PMID 35198065, 2022). "Upregulation of CUL4B enhances immune responses in germinal center B cells, promoting γ-herpesvirus infection and lymphoma cell proliferation." (PMID 40230836, 2025).
osteoporosis (2 papers, 2022 to 2023). A condition of reduced bone mass, with decreased cortical thickness and a decrease in the number and size of the trabeculae of cancellous bone (but normal chemical composition), resulting in increased fracture incidence. "Collectively, this study reveals CUL4B-mediated epigenetic regulation of the osteogenic or adipogenic commitment of MSCs, which has therapeutic implications in osteoporosis." (PMID 37268647, 2023). "Our work reveals a new epigenetic mechanism underlying the regulation of the osteo-adipogenic balance of MSC differentiation and suggests CUL4B as a potential therapeutic target in osteoporosis treatment." (PMID 37268647, 2023). "In addition, CUL4B is responsible for long noncoding RNA Nron-mediated ERα protein stability in osteoporosis." (PMID 36212422, 2022).
pleural mesothelioma (2 papers, 2023 to 2025). A neoplasm that arises from the mesothelial cells of the pleura. "In pleural mesothelioma, CUL4B overexpression is associated with worse patient outcomes, and its downregulation reduces tumor cell proliferation and increases cell death by regulating TGF-β1 expression." (PMID 40230836, 2025).
adenoma (1 paper, 2025). A neoplasm arising from the epithelium. "However, neutralizing MDSC function restores the tumor-prone microenvironment, diminishing adenoma formation, thereby underscoring the pivotal role of MDSCs in modulating the consequences of CUL4B deficiency." (PMID 40230836, 2025). "In CUL4B-deficient intestinal epithelium, G-CSF, a potent recruiter of MDSCs, is upregulated, fostering a tumor-prone environment through enhanced MDSC recruitment and promotion of ApcMin/+ adenoma formation." (PMID 40230836, 2025). "The introduction of MDSCs into the organoid culture system rescued the inconsistent phenotype, reversing Il6/Cox2 expression, and providing novel insights into the intricate interplay between CUL4B, MDSCs, and the TME in the context of ApcMin/+ adenoma development." (PMID 40230836, 2025). "In an intriguing twist, the absence of CUL4B in intestinal epithelium accelerates the development of ApcMin/+ adenomas." (PMID 40230836, 2025).
anencephaly (1 paper, 2019). A rare neural tube defect during pregnancy, resulting in the absence of a large portion of the brain and skull in the fetus. "Our findings also indicated that the downregulation of CUL4B resulted in a loss of H2AK119ub1 both in RA-induced mouse anencephaly and in human anencephaly samples." (PMID 30992047, 2019). "Notably, the expression of HOXA7, HOXA10, and HOXB7 genes was negatively correlated with CUL4B levels in human anencephaly NTD cases." (PMID 30992047, 2019). "In addition, upregulation of HOX genes was observed along with lower levels of CUL4B-mediated H2AK119ub1 in both mouse and human anencephaly NTD cases." (PMID 30992047, 2019). "Notably, the expression of HOXA10 genes was negatively correlated with CUL4B levels in human anencephaly NTD cases." (PMID 30992047, 2019). "In addition, upregulation of HOX genes was observed along with aberrant levels of CUL4B-mediated H2AK119ub1 in both mouse and human anencephaly NTD cases." (PMID 30992047, 2019).
autoimmune disease (1 paper, 2025). A disorder resulting from loss of function or tissue destruction of an organ or multiple organs, arising from humoral or cellular immune responses of the individual to their own tissue constituents. "Additionally, CUL4B promotes the pathology of adjuvant-induced arthritis in rats through the canonical Wnt signaling, further emphasizing its role in autoimmune diseases." (PMID 40230836, 2025). "CUL4B plays a significant role in T cell regulation and autoimmune diseases." (PMID 40230836, 2025). "In disease pathogenesis, CUL4B limits MDSCs to enhance anti-tumor effects, and its inhibition in experimental autoimmune encephalomyelitis (EAE) models have demonstrated beneficial effects, underscoring its potential therapeutic significance in autoimmune diseases." (PMID 40230836, 2025).
benign thyroid tumors (1 paper, 2025). "Our results revealed that CUL4B had the highest expression level in ATC, followed by PTC, and lowest in normal or benign thyroid tumors." (PMID 40203790, 2025).
cardiomyopathy (1 paper, 2024). A disease of the heart muscle or myocardium proper. "We consider the regulation of Pip4k2c, Ehmt2, Gper1, Dicer 1, Cul4b, Fyco1, Gn3l and TNNT2 in the context of doxorubicin-induced cardiomyopathy as particularly relevant." (PMID 39285385, 2024).
cutaneous squamous cell carcinoma (1 paper, 2022). "This study investigated whether lncRNA NEAT1 could inhibit the proliferation of cutaneous squamous cell carcinoma (CSCC) cells by targeting miR-342-3p/CUL4B, thereby affecting the occurrence and development of CSCC." (PMID 35909905, 2022).
developmental delay (1 paper, 2012). "Unexpectedly, we observed that Cul4b heterozygous mice were also affected, as reflected by their recovery at a lower than expected ratio and by their remarkable developmental delay at birth." (PMID 22606329, 2012). "Cul4b heterozygotes were also affected, as reflected by their recovery at a reduced ratio at birth and by their developmental delay." (PMID 22606329, 2012). "This developmental delay in Cul4b heterozygous mice is in contrast to human carriers, whose body sizes are in normal range in their childhood." (PMID 22606329, 2012). "Cul4b heterozygotes were recovered at a reduced ratio and exhibited a severe developmental delay." (PMID 22606329, 2012). "The fact that Cul4b heterozygous mice were smaller in size at birth but could catch up gradually suggests that developmental delay is primarily due to factor(s) that operate during prenatal development." (PMID 22606329, 2012). "The placentas in Cul4b heterozygotes were disorganized and were impaired in vascularization, which may contribute to the developmental delay." (PMID 22606329, 2012). "In addition, Cul4b heterozygotes were recovered in deficit and those that survive to term exhibited a developmental delay." (PMID 22606329, 2012).
experimental autoimmune encephalomyelitis (1 paper, 2025). An autoimmune demyelinating disease of the central nervous system that is produced experimentally in animals by the injection of homogenized brain or spinal cord in Freund's adjuvant. "Additionally, experimental autoimmune encephalomyelitis (EAE) serves as a model for multiple sclerosis (MS), highlighting the complex interaction between immunopathological and neuropathological mechanisms, and the role of CUL4B in these processes." (PMID 40230836, 2025).
hepatitis B (1 paper, 2021). "The hydrodynamics-based hepatitis B model in Cul4b transgenic or conditional knockout mice indicated that CUL4B promoted HBV replication (P < 0.05)." (PMID 33969670, 2021).
Infertility (1 paper, 2025). "Next, to further examine the molecular mechanism underlying the infertility of Sox2-Cre+/−;Cul4bf/+ mice, we determined whether Cul4b deletion affected steroidogenesis in mouse ovaries." (PMID 39737063, 2025). "Global (Sox2-Cre) or germ cell-specific (Vasa-Cre) Cul4b knockout male mice are infertile with impaired spermatozoa motility and spermatogonial stemness." (PMID 39737063, 2025).
ischemia (1 paper, 2024). A hypoperfusion of the BLOOD through an organ or tissue caused by a PATHOLOGIC CONSTRICTION or obstruction of its BLOOD VESSELS, or an absence of BLOOD CIRCULATION. "To figure out whether CUL4B upregulation is specific to cisplatin-induced injury, we adopted another commonly-used AKI model, ischemia reperfusion injury (IRI)." (PMID 39695153, 2024).
lentivirus infection (1 paper, 2022). Virus diseases caused by the Lentivirus genus. "We perform dose-dependent lentivirus infection of shIrgm1 in KOIEC organoids to clarify that CUL4B regulates Wnt regulation through IRGM1." (PMID 35197566, 2022).
lung squamous cell carcinoma (1 paper, 2020). "Our previous study showed that CUL4A and CUL4B had a strong association with tobacco smoking risk in lung squamous cell carcinoma (SCC) and small cell lung carcinoma (SCLC)." (PMID 32587774, 2020).
melanoma (1 paper, 2018). A malignant, usually aggressive tumor composed of atypical, neoplastic melanocytes. "To exclude technical problems in our experiments, we also used a human melanoma cell line A375 as a control to determine the localization patterns of RelA, RelB, and CUL4B." (PMID 29377600, 2018).
microcephaly (1 paper, 2024). A congenital or acquired developmental disorder in which the circumference of the head is smaller than normal for the person's age and sex. "In the present study, we found impaired growth of the patient-derived CUL4B-deficient cerebral organoids, which was consistent with microcephaly presented in our patients." (PMID 38331954, 2024).
Parkinson disease (1 paper, 2023). A progressive degenerative disorder of the central nervous system characterized by loss of dopamine producing neurons in the substantia nigra and the presence of Lewy bodies in the substantia nigra and locus coeruleus. "Further GSEA insights, based on KEGG terms, indicated CUL4B’s involvement in processes related to the ribosome, oxidative phosphorylation, olfactory transduction, Parkinson’s disease, and primary immunodeficiency." (PMID 38075690, 2023).
peritonitis (1 paper, 2024). Inflammation of the peritoneum (tissue that lines the abdominal wall and covers most of the organs in the abdomen). "Myeloid depletion of CUL4B exacerbates lipopolysaccharide (LPS)-induced peritonitis and septic shock." (PMID 39695153, 2024).
Prader-Willi syndrome (1 paper, 2022). "The phenotypic analysis was similarly extended to additional syndromes with molecular or clinical overlap with CHUJANS, namely CUL4B-related disorder and Prader-Willi syndrome (OMIM #176270)." (PMID 36726590, 2022).
skin squamous cell carcinoma (1 paper, 2022). A carcinoma arising from the squamous cells of the epidermis. "This study is the first to demonstrate that the lncRNA NEAT1, as a ceRNA, affects the proliferation of skin squamous cell carcinoma cells through the miR-342-3p/CUL4B/PI3K-Akt signaling pathway." (PMID 35909905, 2022).
thyroid tumor (1 paper, 2025). A benign or malignant neoplasm affecting the thyroid gland. "In this study, we investigated the expression and biological functions of CUL4B in thyroid tumors for the first time." (PMID 40203790, 2025).
viral infection (1 paper, 2023). "We sought to establish whether Cul4b deficiency might perturb CTL function during viral infection." (PMID 37925424, 2023). "Specifically, Cul4b-deficiency resulted in a nearly complete collapse in effector and memory differentiation of CD8+ T cells shortly after viral infection." (PMID 37925424, 2023). "Cul4b deficiency resulted in a decrease of CD44+CD8+ effector/memory T cells in steady-state, prompting us to explore whether Cul4b plays a role in CD8+ T-cell expansion and effector/memory T cell maintenance following viral infection." (PMID 37925424, 2023). "Supporting this, we found that Cul4b was required for the early expansion of CD8+ T cells and mice lacking Cul4b in their T cells were unable to clear viral infection." (PMID 37925424, 2023). "Supporting the importance of Cul4b in CD8+ T cell anti-viral activity, mice lacking Cul4b in T cells were unable to clear virus (LCMV or Ectromelia), and after adoptive transfer, Cul4b-deficient LCMV-specific CD8+ T cells were unable to expand into memory or effector cells following virus infection." (PMID 37925424, 2023).